ERBB2 (erb-b2 receptor tyrosine kinase 2)
Diseases named in the same sentence as ERBB2 in open-access papers (continued):
Sharing a sentence is not in itself a finding about the gene and the disease.
breast tumors (continued). "ErbB2-driven breast tumors lacking LKB1 display elevated mTORC1 activity." (PMID 24280377, 2013). "Clinically, this subset of breast tumors is defined by high level expression of HER2 on the plasma membrane of >10% of the cells within a tumor, assessed by immunohistochemistry, and/or by amplification of the ERBB2 gene, as evidenced by fluorescent in situ hybridization." (PMID 24223926, 2013). "However, clinical information such as hormone receptor or ERBB2 status of breast tumor samples is not invariably provided with their global gene expression profiles." (PMID 22022496, 2011). "However, a significant fraction (∼60%) of patients with metastatic breast tumors does not respond to the treatment, highlighting the necessity for continued investigation of ERBB2-mediated modifications in breast cells." (PMID 21731642, 2011). "As the majority of these ER+ tumours were found to express low and/or negative erbB2 levels, these findings directly support our cell line work and suggest that an association between erbB3 and IRS-1 may well occur within ER+ breast tumours." (PMID 21939528, 2011). "Breast tumors scoring at 2+ or 3+ by IHC should be analyzed by FISH for ERBB2, preferably with a dual-probe system capable of detecting aberrations in chromosome 17 that could affect ERBB2 expression." (PMID 15743507, 2005). "Although this might reflect the challenges associated with IHC detection of phosphorylated epitopes in archival tissues, ERBB2 is not amplified or mutated in any of these prostate tissues, and thus the pathologic grading standards applied to HER2+ lung and breast tumors may not necessarily apply." (PMID 40906535, 2025). "Moreover, it was found that breast tumor cells circulating in patient's blood are ErbB2-positive in a significant number of cases whereas the cells composing respective primary tumors are often ErbB2-negative." (PMID 29285258, 2017). "This is most likely due to heterogeneity of breast tumors, tumor sample sets, and the fact that the strongest correlation is in ER-positive 16 or in luminal B tumors 17, as observed in this study, as well as lower or nonexistent correlation in other subtypes such as the ERBB2 and basal subtypes." (PMID 24156016, 2013). "Further investigations, however, are needed to determine whether breast tumors with ERBB2 2+ or 3+ IHC score without gene amplification but with high levels of AP-2α and YY1 have a particular behaviour regarding clinical outcome and response to Herceptin treatment." (PMID 18218085, 2008). "Amongst the well-documented BC subtypes, HER2-positive and triple-negative (defined by the absence of ER, PR, HER2/ERBB2 expression) breast tumors present distinct challenges in diagnosis and therapeutic needs." (PMID 31508500, 2019). "In one published analysis of a large collection of primary breast tumor samples, TOP2A alterations were reported in 23% of all tumors, regardless of their ERBB2 status: 12% had TOP2A amplification and 11% had TOP2A deletion." (PMID 18702822, 2008). "FTY720 also reduced HDAC activity in breast tumors, concomitant with marked production of nuclear FTY720-P compared with FTY720 and increased mRNA levels of ERα and PR, without affecting expression of ErbB2." (PMID 26053034, 2015). "Three-quarters of triple-negative BCs harbour at least one amplicon, however, their recurrence rates are lower than those of high-level CNAs found in ER-positive/ HER2-negative and HER2-positive BC subtypes (e.g. ERBB2-amplicon in HER2, and CCND1 and FGFR1 in luminal breast tumours)." (PMID 23151021, 2012). "In this context, we have shown that the NF-κB signature performed better in separating ER-negative breast tumours from ER-positive breast tumours as well as EGFR- and/or ErbB2-overexpressing breast tumours from their EGFR-negative and ErbB2-negative counterparts." (PMID 17848951, 2007).
breast tumors (continued). "In addition, nearly all breast tumours having EGFR and/or ErbB2 overexpression were contained in the IBC-rich sample cluster: 17 out of 33 EGFR and/or ErbB2-positive samples in the IBC-rich cluster versus 25 out of 26 EGFR- and ErbB2-negative samples in the IBC-poor cluster (Pearson χ2, P<0.0001)." (PMID 17848951, 2007).
gastric cancer (2,245 papers, 1990 to 2026). A primary or metastatic malignant neoplasm involving the stomach. "Our analysis of the C-CAT database provides important insights into the clinical significance of the ERBB2 R678Q mutation in regard to gastric cancer treatment." (PMID 40699829, 2025). "The RNA sequencing data highlight several key proteins—HIF1A, HSP90AA1, PTGS2, MMP9, and ERBB2—which are associated with various stages of gastric cancer progression and align with established biomarkers and pathways." (PMID 40141751, 2025). "This analysis of the C-CAT database suggests that the ERBB2 R678Q mutation, present in approximately 1% of gastric cancer cases, is associated with a significantly reduced response to oxaliplatin-based therapy." (PMID 40699829, 2025). "We analyzed the genetic alterations identified through cancer genome profiling tests in the 40 gastric cancer cases with ERBB2 R678Q mutations." (PMID 40699829, 2025). "ERBB2 amplification has been implicated in the carcinogenesis of diverse malignancies, including breast, lung, and gastric cancers, and in approximately 3% of cases of mCRC." (PMID 40051563, 2025). "ERBB2, also identified as an upregulated gene in gastric cancer, encodes a 185 kDa transmembrane glycoprotein belonging to the epidermal growth factor receptor (EGFR) family." (PMID 40141751, 2025). "In this study, we aimed to characterize the prevalence, molecular context, and treatment implications of the ERBB2 R678Q mutation in gastric cancer patients, using the C-CAT database." (PMID 40699829, 2025). "This study provides real-world evidence supporting the potential clinical relevance of this specific ERBB2 mutation in treatment decision making for gastric cancer." (PMID 40699829, 2025). "In gastric cancer, ERBB2 amplification on eccDNA has been associated with poor prognosis in ERBB2-positive patients." (PMID 39202666, 2024). "According to OMIM and Orphanet, one gene among eleven enriched genes in this cluster, ERBB2 and associated pathways are linked with a wide range of cancers, including lung adenocarcinoma, gastric cancer, glioblastoma, and ovarian cancer." (PMID 38271343, 2024). "Amplification of ERBB2 also occurs in 10–30% of gastric cancers and has been associated with different types of cancer, such as ovary, colon, and bladder cancers." (PMID 38216592, 2024). "We also assessed the associations between ERBB2 amplification and local immune environment factors in gastric cancer patients from the TCGA dataset." (PMID 37325934, 2023). "HER2, encoded by the ERBB2 gene, is overexpressed/amplified in approximately 15% of gastric cancer patients." (PMID 37325934, 2023). "Amplification of the ERBB2 gene, which leads to the overproduction of HER2 protein, is associated with the development and progression of certain types of cancer, particularly breast and gastric cancer." (PMID 39516338, 2023). "The two gastric carcinoma cases showed an ERBB2 R678Q pathogenic variant with a PIK3CA E542K and KRAS G12V variants." (PMID 36125633, 2023). "In a more detailed analysis, we found patients with ERBB2 mutation had significantly higher TMB compared with non-ERBB2 mutation in bladder/urinary tract cancer (p = 0.0045), stomach cancer (p = 0.0045), and colorectal cancer (p = 0.0021) respectively." (PMID 35911441, 2022). "Impaired ERBB2 expression or function has been implicated in the progression of breast and gastric cancers, mainly through targeting the PI3K/AKT and MAPK pathways." (PMID 36033386, 2022). "Somatic mutations in ERBB2 are reported in many solid tumor malignancies, most commonly in bladder, uterine, colon, and gastric cancers; mutations in hematologic diseases are rare but have been reported." (PMID 34209587, 2021).
gastric cancer (continued). "Studies have shown that the expansion of ERBB2 is associated with a poor prognosis of gastric cancer." (PMID 34485109, 2021). "Combined with somatic hotspot mutations, ERBB2 was activated in 9 of the 90 gastric cancers (10%), KRAS was in 6 (7%), and PIK3CA was in 4 (4%)." (PMID 34873204, 2021). "The upstream gene for the circRNA in ERBB2, and alternative circRNA from this site has previously been implicated in the gallbladder and gastric cancer and so this was named cholangiocarcinoma associated circular RNA 1 (circ-CCAC1) by the authors." (PMID 33158116, 2020). "For HER2-gastric cancer, the high expression of ERBB2, VIM, or IFI44 was associated with worse overall survival (P < 0.05)." (PMID 31949544, 2019). "For the diagnosis, upregulation of GPAA1 is closely associated with poor prognosis in gastric cancer, and its expression is positively related ERBB2." (PMID 31118109, 2019). "In this work, we present the results of the association analysis of five ERBB2 SNPs with the risk of gastric cancer." (PMID 31116314, 2019). "For all gastric cancer cases, our results showed that high ERBB2 expression was associated with the worse overall survival of GC patients, VIM, IFI44, IFIT2, and MX1 showed similar associations (P < 0.05)." (PMID 31949544, 2019). "The HER2 proto-oncogene, named HER2/neu or (C-)ERBB2, was found to have upregulated expression in gastric cancer and to be closely associated with poor survival in patients with advanced gastric carcinoma." (PMID 31118109, 2019). "In conclusion, the present study has partially clarified the association between miR-1296-5p and ERBB2-positive gastric cancer." (PMID 28099468, 2017). "ErbB2 overexpression has been described in several types of neoplastic processes, including breast and gastric cancer amongst others, and is associated with increased aggressiveness, significantly shortened disease-free and overall survival." (PMID 28306722, 2017). "Among the 200 primary gastric carcinomas of the referred dataset, a statistically highly significant positive association (Spearman’s rank correlation p < 0.0001) between the expression of ERBB2 and FUT3 genes was observed." (PMID 29143776, 2017). "Recently, somatic mutations in ErbB3 with transforming potential were reported in colon and gastric cancers, however, these variants were still functionally dependent on ErbB2." (PMID 27447549, 2016). "Among them, ERBB2 (HER2) is frequently amplified and over-expressed in gastric cancers, and amplification of HER2 was strongly associated with poor survival, particularly in the intestinal type of gastric cancer." (PMID 26360582, 2015). "In conclusion, the present study has partially clarified the associations between miR-375 and ERBB2-positive gastric cancer." (PMID 24926380, 2014). "ErbB2 is known to be associated with poor prognosis in gastric cancer, flotillins have been described to be associated with tumor genesis." (PMID 23658725, 2013). "Examples in treatment of solid tumors include ERBB2 (HER2) gene amplification in breast and gastric cancer, EGFR mutation in non-small cell lung cancer, and KRAS mutation in colorectal cancer." (PMID 23700467, 2013). "Association of ERBB2 expression with the clinicopathological features of gastric cancer has been investigated in several studies." (PMID 21811585, 2011). "ERBB2 amplification was associated with gastric carcinomas of intestinal type (P=0.007) and with an expansive growth pattern (P=0.021)." (PMID 19156142, 2009). "A statistically significant association was found between ERBB2 amplification and worse survival in patients with expansive gastric carcinomas (P=0.011)." (PMID 19156142, 2009). "Many PTK genes are proto-oncogenes and some of them are associated with human cancer progression, including erbB2/neu in breast cancer and met in gastric cancer." (PMID 12671705, 2003).
gastric cancer (continued). "Despite these limitations, our findings might provide potential evidence for the clinical relevance of ERBB2 R678Q mutations in gastric cancer." (PMID 40699829, 2025). "In addition, an insufficient immune microenvironment in gastric cancer is associated with HER2-positivity or tumors having ERBB2 genetic aberrations." (PMID 39679910, 2025). "This big data analytics approach can elucidate subtle clinical conundrums, including the disparities in prognosis between distal and proximal gastric cancer patients and the prognostic differences associated with ERBB2 expression in gastric cancer, as exemplified by our research findings." (PMID 39199766, 2024). "The results of the present study indicate that ERBB2 expression level detection, associated with quantified miR-375, may be used to enhance the accuracy of clinical gastric cancer classification." (PMID 24926380, 2014). "Thus, co‐amplification of CDK12 and ERBB2 may be a potential mechanism underlying trastuzumab resistance in gastric cancer." (PMID 37325934, 2023). "In HER2-positive breast and gastric cancers, ERBB2-driven STAT3 activation is a key mechanism contributing to tumor aggressiveness and resistance to targeted therapy." (PMID 41516350, 2026). "Given the proximity of CDK12 to ERBB2 on chromosome 17q12, co-amplification events likely contribute to its overexpression in HER2-positive gastric cancers." (PMID 41491919, 2026). "Recently, the U.S. Food and Drug Administration (FDA) approved the use of ERBB2-targeted drugs to treat breast and gastric cancers with ERBB2 amplification." (PMID 40051563, 2025). "HER2 (ERBB2) overexpression or gene amplification is observed in 10–30% of gastric cancer cases, leading to a more aggressive disease that is difficult to manage." (PMID 40563418, 2025). "The landmark ToGA trial established trastuzumab plus chemotherapy as the standard first-line treatment for ERBB2-positive advanced gastric cancer, demonstrating significant improvements in overall survival compared to chemotherapy alone." (PMID 40699829, 2025). "While therapeutic strategies targeting other ERBB receptors (e.g., HER2/ERBB2) have shown success in treating breast and gastric cancers, ERBB4 remains relatively underexplored." (PMID 40806544, 2025). "The target proteins implicated in gastric cancer, specifically HIF1A, HSP90AA1, MMP9, ERBB2, and PTGS2, were matched with the key metabolites from the Vaccinium genus, including cyanidin 3-O-glucoside, ursolic acid, resveratrol, scopoletin, and (+)-catechin." (PMID 40141751, 2025). "Multiple factors can induce apoptosis in gastric cancer cells by downregulating ERBB2 expression, inhibiting cell proliferation and growth." (PMID 41305721, 2025). "According to our observations, Chb‐M' was a novel drug candidate that enables the CROX approach, consistently inactivating the ErbB2/HER2 signaling pathway, and is effective on several HER2‐positive gastric cancer cell lines." (PMID 40171874, 2025). "Previous studies have established that afatinib sensitivity correlates with EGFR/ERBB2 co-amplification in gastric cancer, highlighting the prospective therapeutic potential of pan-HER inhibitors in clinical practice." (PMID 40830980, 2025).